ZNF768 (zinc finger protein 768)
Description:
Binds to mammalian-wide interspersed repeat (MIRs) sequences in euchromatin and promoter regions of genes at the consensus sequence 5'-GCTGTGTG-[N20]-CCTCTCTG-3', consisting of two anchor regions connected by a linker region; the linker region probably does not contribute to the binding specificity. Required for cell homeostasis. May be involved in transcriptional regulation (Probable).
Synonyms: FLJ23436
Tractability: PROTAC: ubiquitination databases record sites on it.
Gene: Protein-coding gene on chromosome 16 (30,524,004 to 30,526,821, reverse strand). Ensembl gene ENSG00000169957.
Subcellular location: Nucleus; Chromosome
Subcellular location (Human Protein Atlas): Nucleoplasm; Vesicles
Gene Ontology:
Molecular function: protein binding; RNA binding; sequence-specific double-stranded DNA binding; DNA-binding transcription factor activity, RNA polymerase II-specific; RNA polymerase II transcription regulatory region sequence-specific DNA binding; DNA binding
Biological process: regulation of transcription by RNA polymerase II; transcription by RNA polymerase II
Cellular component: chromosome; nucleus
Genetic constraint (gnomAD): Loss-of-function variants: 12 observed, 38.93 expected, observed/expected ratio (o/e) 0.31, 90% interval 0.2 to 0.5. The synonymous counts are far from expectation, so gnomAD's model fits this gene poorly and the ratio says little. Missense variants: 613 observed, 738.25 expected, observed/expected ratio (o/e) 0.83, 90% interval 0.78 to 0.89. Synonymous variants: 360 observed, 292.52 expected, observed/expected ratio (o/e) 1.23, 90% interval 1.13 to 1.34.
Homologues: Orthologues: chimpanzee ZNF768 (99% identical), macaque ZNF768 (99% identical), dog ZNF768 (94% identical), pig ZNF768 (94% identical), rat Zfp768 (92% identical), mouse Zfp768 (90% identical), guinea pig ZNF768 (87% identical). Paralogues in human: ZNF572 (34% identical), ZNF287 (34% identical), ZKSCAN7 (33% identical), ZNF774 (33% identical), ZNF852 (32% identical), ZNF214 (32% identical), ZNF17 (31% identical), ZNF34 (31% identical), ZNF527 (31% identical), ZNF530 (31% identical), ZNF285 (31% identical), ZNF416 (31% identical), and 38 more.
Diseases named in the same sentence as ZNF768 in open-access papers:
ZNF768 is named in the same sentence as 24 diseases in open-access papers, as found by Europe PMC text mining. Sharing a sentence is not in itself a finding about the gene and the disease. The quoted sentences say what the papers report.
colorectal cancer (4 papers, 2015 to 2021). A primary or metastatic malignant neoplasm that affects the colon or rectum. "We have previously identified autoantibodies to ZNF346, ZNF638, ZNF700 and ZNF768 in colorectal cancer patients using a 37,830-clone recombinant human protein array." (PMID 25875936, 2015). "In the current study, we validated the presence of autoantibodies to ZNF346, ZNF638, ZNF700 and ZNF768 in colorectal cancer in an independent and larger patient cohort using the well-established ELISA platform." (PMID 25875936, 2015). "In this study we assess the zinc finger proteins ZNF346, ZNF638, ZNF700 and ZNF768 as capture antigens for the detection of autoantibodies in colorectal cancer." (PMID 25875936, 2015). "Our results indicate that zinc finger proteins ZNF346, ZNF638, ZNF700 and ZNF768 are suitable for use as capture antigens in a blood-based biomarker assay for colorectal cancer." (PMID 25875936, 2015). "Autoantibodies against ZNF768 are also detected in the plasma of patients with colorectal cancer." (PMID 34439288, 2021).
lung carcinoma (3 papers, 2021 to 2025). "Interestingly, ZNF768 levels were positively associated with tumor grade in this model of lung cancer." (PMID 40133474, 2025). "In-house validation studies using a lung cancer cohort confirmed that ZNF768 protein levels are elevated in tumors." (PMID 40133474, 2025). "In a second set of experiments, we took advantage of a well-described model of lung cancer to test the role of ZNF768 overexpression on carcinogenesis." (PMID 40473701, 2025). "In lung cancer, we found that ZNF768 protein levels positively correlate with Ki-67 and other proliferative clinicopathological features." (PMID 40133474, 2025). "Overall, these results support a strong connection between ZNF768 expression and proliferation in lung cancer cell lines." (PMID 34439288, 2021). "Collectively, these results highlight a direct effect of ZNF768 on proliferation in lung cancer cell lines and further support a link between ZNF768 and proliferative clinicopathological features in LUAD." (PMID 34439288, 2021). "Further supporting the proliferative signature associated with ZNF768 in LUAD, knockdown of ZNF768 in different lung cancer cell lines severely impaired proliferation and decreased the expression of key cell cycle effectors." (PMID 34439288, 2021). "The striking loss of proliferative capability and the reduction in the expression of proliferative genes in lung cancer cells depleted from ZNF768 support this conclusion." (PMID 34439288, 2021). "Supporting a role for ZNF768 in promoting proliferation, we report that ZNF768 depletion severely impairs proliferation in several lung cancer cell lines in vitro." (PMID 34439288, 2021). "Supporting a role for ZNF768 in promoting proliferation, ZNF768 depletion severely impairs proliferation in several lung cancer cell lines." (PMID 34439288, 2021). "Furthermore, depleting ZNF768 expression in lung cancer cell lines severely repressed proliferation." (PMID 40133474, 2025). "Our results support a central role for ZNF768 in promoting the proliferation of lung cancer cells." (PMID 34439288, 2021). "Based on the impact of ZNF768 depletion on lung cancer cells, we aimed to determine whether ZNF768 depletion also altered the expression of genes involved in cell cycle progression." (PMID 34439288, 2021). "Given the correlation between ZNF768 levels and proliferative clinicopathological features in LUAD, we investigated whether repressing ZNF768 could impact proliferation of lung cancer cells in vitro." (PMID 34439288, 2021).
fibrosarcoma (2 papers, 2025). A malignant mesenchymal fibroblastic neoplasm affecting the soft tissue and bone. "First, wild-type and ZNF768 overexpressing mice were injected in the hind limb with 3-methylcholanthrene (3MC), a carcinogen that induces fibrosarcoma development." (PMID 40473701, 2025). "Here, high ZNF768 protein levels were observed in fibrosarcoma induced by the chemical carcinogen 3MC and in LUAD induced by oncogenic KRASG12D." (PMID 40133474, 2025). "First, overexpression of ZNF768 in fibrosarcoma of WB-ZNF768-Tg mice was confirmed." (PMID 40473701, 2025). "Here, we observed that ZNF768 levels were highly increased in fibrosarcoma compared to normal muscle." (PMID 40133474, 2025). "However, ZNF768 overexpression was not sufficient to promote 3-methylcholantrene-induced fibrosarcoma and KRASG12D-induced lung adenocarcinoma in mice." (PMID 40473701, 2025).
acute myeloid leukemia (1 paper, 2021). Acute myeloid leukemia (AML) is a group of neoplasms arising from precursor cells committed to the myeloid cell-line differentiation. "Only two cancer types showed lower ZNF768 expression in tumors compared to normal tissue, namely acute myeloid leukemia (LAML) and testicular germ cell tumors (TGCT)." (PMID 34404770, 2021).
autoimmune disease (1 paper, 2015). A disorder resulting from loss of function or tissue destruction of an organ or multiple organs, arising from humoral or cellular immune responses of the individual to their own tissue constituents. "Autoantibodies to other zinc finger proteins were also frequently detected in cancer and autoimmune disease; however, there is a paucity of literature on autoantibodies specific to zinc finger proteins ZNF700 and ZNF768." (PMID 25875936, 2015).
colon cancer (1 paper, 2022). "However, in the current state of the research, there are still many ZFPs whose mechanisms of action in colon cancer are not fully understood, and more mechanisms need to be further studied, such as ZNF146, ZNF511, ZNF346, ZNF638, ZNF700, and ZNF768." (PMID 36358661, 2022).
prostate adenocarcinoma (1 paper, 2021). "Many cancer types, including colorectal, breast and prostate adenocarcinomas, also displayed strong nuclear staining for ZNF768." (PMID 34404770, 2021).
cancer (7 papers, 2015 to 2025). A tumor composed of atypical neoplastic, often pleomorphic cells that invade other tissues. "Because ZNF768 levels are elevated in tumors, we tested the impact of ZNF768 loss on cancer development in mice." (PMID 40133474, 2025). "We have shown that this is also the case in cancer mouse models where ZNF768 is overexpressed in tumors and associated with tumor grade." (PMID 40133474, 2025). "Additional studies are needed to define which cancer types are affected by ZNF768 loss and to precise the mechanisms involved in these effects." (PMID 40133474, 2025). "We also found that ZNF768 loss increased expression of cell cycle inhibitor p21 in a carcinogen-induced cancer mouse model and repressed lung tumor development in response to oncogenic KRAS." (PMID 40133474, 2025). "Altogether, our findings show that ZNF768 protein levels are elevated in LUAD, that ZNF768 associates with proliferative markers in this cancer and that this transcription factor is required to support cancer cell proliferation." (PMID 34439288, 2021). "The overall tumor burden of the lungs was significantly decreased in ZNF768 null mice following cancer induction." (PMID 40133474, 2025). "We also show that ZNF768 deletion repressed tumor development in a KRASG12D-induced cancer mouse model." (PMID 40133474, 2025). "Altogether, these results show that overexpression of ZNF768 is common in various types of cancers in mice." (PMID 40133474, 2025). "Here, we show that ZNF768 deletion was sufficient to repress lung tumor development in a KRASG12D-induced cancer mouse model." (PMID 40133474, 2025). "Because ZNF768 levels are often overexpressed in cancer, we assessed tumor development in WB-ZNF768-Tg mice." (PMID 40473701, 2025). "We have previously shown that ZNF768 is amplified and/or overexpressed in various cancer types in humans." (PMID 40133474, 2025). "Owing to the close relationship between ZNF768 and cell proliferation, the expression level of this transcription factor was analysed in various cancer using public databases." (PMID 40133474, 2025). "In this cancer, ZNF768 correlates with the mitotic score and Ki-67 expression, two classical markers of proliferation." (PMID 40133474, 2025). "Altogether, these results highlight a new role for ZNF768 in repressing senescence and promoting cancer cell proliferation." (PMID 34439288, 2021). "Our study, that extends previous in vitro data, provides the first clinical observations supporting a possible role for ZNF768 in promoting cancer cell proliferation and tumor development in humans." (PMID 34439288, 2021). "Altogether, these results show that reducing ZNF768 levels is sufficient to trigger senescence in normal and cancer cell lines in vitro." (PMID 34404770, 2021). "As recently discussed, preliminary analyses through the Human Protein Atlas resource showed that several cancers display high ZNF768 protein expression." (PMID 34439288, 2021). "In a first attempt to characterize ZNF768 functions, normal and cancer cell lines of different origins were transduced with lentiviruses expressing short-hairpin RNA (shRNA) to deplete ZNF768." (PMID 34404770, 2021). "This analysis revealed that ZNF768 expression is significantly elevated in 10 out of the 31 cancer types analyzed." (PMID 34404770, 2021). "Because ZNF768 gene is rarely amplified in these tumors, these results suggest that post-transcriptional and/or post-translational processes probably take place to promote ZNF768 protein levels in cancer." (PMID 34439288, 2021).
cancer (continued). "Altogether, these results indicate that ZNF768 is often amplified and/or overexpressed in various cancer types in humans." (PMID 34404770, 2021). "We found that ZNF768 levels are often elevated in LUAD and that ZNF768 protein levels positively correlate with Ki-67 and other proliferative clinicopathological features in this cancer." (PMID 34439288, 2021). "An interesting question that emerges from these observations relates to the mechanisms driving ZNF768 expression cancer cells." (PMID 34439288, 2021). "Studies in cancer cells in vitro showed that alteration in ZNF768 levels deeply impacts gene expression." (PMID 34404770, 2021). "A marked decrease in the expression of key proliferative genes was observed in cancer cell lines depleted from ZNF768." (PMID 34439288, 2021). "Further studies are required to establish the direct role of ZNF768 in human cancer and its possible mechanisms of action in vivo." (PMID 34439288, 2021). "This safeguard mechanism against neoplasia is bypassed by cancer cells, that often overexpress ZNF768." (PMID 34404770, 2021). "Supporting this possibility, analysis of ZNF768 protein levels through the Human Protein Atlas revealed that many human cancers display intense staining for ZNF768." (PMID 34404770, 2021). "Altogether, these results suggest that cancer cells might take advantage of ZNF768 to sustain tumorigenesis." (PMID 40133474, 2025). "ZNF768 is an emerging regulator of cell proliferation whose expression is elevated in human cancer." (PMID 40133474, 2025). "These analyses revealed that ZNF768 overexpression is common in a variety of cancers in humans." (PMID 40133474, 2025). "Defining the precise mechanisms regulating ZNF768 levels may offer novel opportunities to control cell proliferation and fight cancer." (PMID 40133474, 2025). "Following this model, we proposed that the elevation in ZNF768 levels observed in most human cancers may represent a strategy developed by neoplastic cells to evade senescence and support proliferation." (PMID 40473701, 2025). "Aberrant expression of ZNF768 has been observed in multiple types of cancer in mice and humans." (PMID 40473701, 2025). "It is therefore possible that the loss of ZNF768 was not sufficient to repress proliferation in this highly mutagenic and aggressive cancer model." (PMID 40133474, 2025). "Herein, we tested whether ZNF768 overexpression could drive tumor development in basal conditions or in carcinogen- and oncogene-induced cancer mouse models." (PMID 40473701, 2025). "To define whether ZNF768 levels are similarly regulated in mice, we measured ZNF768 levels in two established models of cancer." (PMID 40133474, 2025). "We then assessed whether ZNF768 overexpression could promote tumor development in carcinogen- and oncogene-induced cancer mouse models." (PMID 40473701, 2025). "Although the importance of ZNF768 in supporting cell proliferation and survival has been well demonstrated in cancer cells in vitro, the physiological and pathological roles of ZNF768 in vivo are still unknown." (PMID 40133474, 2025). "Human cancer studies revealed that ZNF768 is often overexpressed in tumors, suggesting that cells might use this protein to bypass senescence, sustain proliferation and promote malignant transformation." (PMID 34404770, 2021). "In order to define whether ZNF768 also affects gene expression profiles in human cancer, we used TCGA data and performed pathway analyses comparing lung tumors with either low or high ZNF768 mRNA expression based on the median for each histological subtypes." (PMID 34404770, 2021).